AR (androgen receptor)
Diseases named in the same sentence as AR in open-access papers (continued):
Sharing a sentence is not in itself a finding about the gene and the disease.
cystic teratoma (1 paper, 2025). "SF1 and AR specifically highlighted the intraneural cell precursors of Leydig cells, which were previously identified in a published case of mature cystic teratoma of the ovary, and the adult ovarian Leydig cells." (PMID 40220034, 2025).
cystitis (1 paper, 2023). Inflammation of the urinary bladder. "In our previous study, we demonstrated that TrkA and p75NTR inhibition via AR and LM respectively improved bladder functional parameters in the same mouse models of cystitis as used presently." (PMID 37701183, 2023).
desmoplastic small round cell tumor (1 paper, 2024). Desmoplastic small round cell tumor (DSRCT) is an aggressive soft tissue cancer that typically arises in serous lined surfaces of the abdominal or pelvic peritoneum, and spreads to the omentum, lymph nodes and hematogenously disseminates especially to the liver. "This study presents a novel mechanism by which androgen receptor (AR) antagonists inhibit the growth of desmoplastic small round cell tumors (DSRCT) independently of AR." (PMID 38575753, 2024).
dilatation (1 paper, 2025). "Both castration and knockout of the AR in BMSCs of male mice reduced cardiac neutrophil accumulation, infarct size, mortality, and cardiac dilatation post-MI." (PMID 39910039, 2025).
Disorder of sex differentiation (1 paper, 2025). "Disorder of sex differentiation (DSD) can result from mutations in sex-determining genes to androgen receptor defects." (PMID 40125104, 2025).
dry eye (1 paper, 2022). "Sex hormone receptors, including AR, PR, ERα, and ERβ, have not only been identified in the human cornea and lacrimal gland but are also implicated in ocular diseases such as dry eye." (PMID 35055103, 2022).
eccrine tumors (1 paper, 2012). "By contrast, none of the eccrine tumors (0/7, 0%) in our series exhibited AR expression." (PMID 23056620, 2012).
eosinophilia (1 paper, 2025). "Additionally, in a mouse model with a mutation in the androgen receptor (AR) gene, rendering the mice unresponsive to androgens, it has been shown that AR signaling reduces house dust mite (HDM)-associated eosinophilia." (PMID 40217954, 2025).
Epstein-Barr virus infection (1 paper, 2022). An infection that is caused by Epstein-Barr virus. "Finally, four significant KEGG enrichment pathways were identified (P < 0.05): beta-Alanine metabolism (SMOX, HIBCH), Pathways in cancer (GLI2, AR, TXNRD3, TRAF3, FGF16), Non-homologous end-joining (MRE11), Epstein-Barr virus infection (TRAF3, PSMD13, SIN3A)." (PMID 36330154, 2022). "Finally, the results of KEGG enrichment analysis showed four significantly enriched pathways (P < 0.05): beta-Alanine metabolism (SMOX, HIBCH), Pathways in cancer (GLI2, AR, TXNRD3, TRAF3, FGF16), Non-homologous end-joining (MRE11), Epstein-Barr virus infection (TRAF3, PSMD13, SIN3A)." (PMID 36330154, 2022).
eye inflammation (1 paper, 2019). "Therefore, we next examined AR expression in the retina in order to explain reduced eye inflammation despite higher catecholamine levels." (PMID 30787395, 2019).
fibromatosis (1 paper, 2011). A poorly circumscribed neoplasm arising from the soft tissues. "Human aggressive fibromatosis tumours were examined for the expression of the androgen receptor, and primary human tumour cell cultures were treated with testosterone." (PMID 21468052, 2011). "We examined RNA from 24 aggressive fibromatosis tumours and protein from 18 of the tumours for expression of the androgen receptor by real-time RT–PCR or western blot analysis using previously reported techniques." (PMID 21468052, 2011). "It explains the observation that male Apc1638N develop larger number of tumours, and suggests that androgen receptor-blocking agents could serve as a novel therapeutic approach to aggressive fibromatosis." (PMID 21468052, 2011).
fluorosis (1 paper, 2017). "To investigate the association of AR with fluorosis, we examined the presence and localization pattern of AR in maturation stage ameloblasts." (PMID 29249975, 2017).
follicular lymphoma (1 paper, 2006). Follicular lymphoma is a form of non-Hodgkin lymphoma characterized by a proliferation of B cells whose nodular structure of follicular architecture is preserved. "Published studies of primary follicular lymphoma specimens have demonstrated that: androgen receptor, SHP1, and death-associated protein kinase genes are commonly methylated." (PMID 17026765, 2006).
Friedreich ataxia (1 paper, 2011). An inherited condition that affects the nervous system and causes movement problems. "This phenomenon was reported some time ago for CAG repeats in the human androgen receptor gene and for GAA repeats in the Friedreich's ataxia gene." (PMID 21347256, 2011).
galactosemia (1 paper, 2017). "Galactosemia obviously activated lens AR (42.13 nmol/hr/100 mg protein), which leads to the accumulation of galactitol (69.84 nmol/g lens weight) and the markedly upregulated AR mRNA (2.38-fold)." (PMID 29038789, 2017). "In vivo, sugar cataract developed more rapidly in galactosemic rats than in diabetic rats, we observed some tiny vesicles appeared in the model lens from the 3rd day, that indicated AR had already been activated by galactosemia and lens osmotic expansion came into being." (PMID 29038789, 2017).
gastrointestinal infections (1 paper, 2023). "In male patients with gastrointestinal infections, testosterone mitigates Th2-dominant responses and promotes Th1 immunity by modulating androgen receptor signaling and cytokine secretion in macrophages and lymphocytes." (PMID 38259843, 2023).
giant cell carcinomas (1 paper, 2023). "The expression of prostatic markers (PSA 5–60%, PSMA 20–80%, AR 90–100%, and NKX3.1 70–100%) identified PGCC as of prostatic origin and allowed to differentiate it from pleomorphic giant cell carcinomas from other organs." (PMID 36600115, 2023).
Gillespie syndrome (1 paper, 2021). "A closer look at the phenotype suggests that the clinical features resemble more Gillespie syndrome caused by both AD and AR variants in the paralog gene ITPR1 (OMIM # 147265)." (PMID 33710394, 2021). "In FIN23-3, a candidate de novo variant [p.(Lys181Glu)] in 1,4,5-triphosphate receptor, type 2 (ITRP2) was identified in the sample from the patient, who has a phenotype resembling Gillespie syndrome caused by both AD and AR variants in ITPR1 (OMIM # 147265)." (PMID 33710394, 2021).
glomerulopathy (1 paper, 2025). "(a) NM_003647.2(DGKE):c.953A>G, p.N318S (MIM#601440), nephrotic syndrome, type 7 (MIM#615008, AR), homozygous.(b) NM_212482.2(FN1):c.5587C>T, p.P1863S (MIM#135600), glomerulopathy with fibronectin deposits 2 (MIM#601894, AD), heterozygous." (PMID 41477467, 2025).
hidradenocarcinoma (1 paper, 2015). A carcinoma with apocrine and less often eccrine differentiation, arising from the sweat glands. "On immunohistochemistry, hidradenocarcinomas are variably positive for androgen receptor (AR), estrogen receptor (ER), progesterone receptor (PR), EGFR (epidermal growth factor receptor), and HER-2 (human epidermal growth factor receptor 2)." (PMID 25815059, 2015). "Hidradenocarcinoma and adenocarcinomas of salivary gland and breast has a histomorphologic overlap, which led to the investigators to compare ER, PR, AR, HER-2/neu status, and gross cystic disease fluid protein levels." (PMID 25815059, 2015).
hospital-acquired infections (1 paper, 2019). "Plasmids specifically have been identified carrying AR genes in hospital-acquired infections, community-acquired outbreaks, and have also been associated with AR genes in isolates from animals raised for consumption." (PMID 31057528, 2019).
hyperlipoproteinemia (1 paper, 2016). An elevated concentration of lipoproteins. "Intervention with flutamide, an androgen receptor (AR) inhibitor, has confirmed that testosterone action via the AR mediates apoB-hyperlipoproteinemia and hypertriglyceridemia, and this appears to be independent of effects on insulin." (PMID 27777929, 2016).
hyperprolactinaemia (1 paper, 2015). "The results we present here also strongly suggest a role of AR is to repress prolactin secretion in males, and that ablating AR from the pituitary removes this repression resulting in a novel model of hyperprolactinaemia." (PMID 25799562, 2015).
hypertrichosis (1 paper, 2014). Excessive hair growth anywhere on the body. "In conclusion, we have studied the hormonal profile and androgen receptor polymorphisms in a group of prepubertal girls with hypertrichosis." (PMID 24745883, 2014). "We performed a hormonal and androgen receptor study in 42 prepubertal girls with hypertrichosis and 29 control girls from 2 to 8 years of age." (PMID 24745883, 2014). "The normal androgen levels in haplotypes 1 and 2 indicates that they may develop hypertrichosis due to enhanced androgen receptor sensitivity." (PMID 24745883, 2014). "The aim of our study was to evaluate the clinical and hormonal characteristics of a large group of girls with hypertrichosis, and to assess the number of CAG and GGC repeats in their androgen receptor gene." (PMID 24745883, 2014).
hypovitaminosis D (1 paper, 2026). "Therefore, in addition to testosterone, other factors may play a role in the skeletal fragility and in the fracture risk, such as hypovitaminosis D, reduced INSL‐3 levels, low estrogen levels, altered AR function and sensitivity and reduced lean mass." (PMID 40191911, 2026).
injury (1 paper, 2016). Damage inflicted on the body as the direct or indirect result of an external force, with or without disruption of structural continuity. "The androgen receptor antagonist, flutamide, is strongly associated with idiosyncratic drug-induced liver injury (DILI)." (PMID 27413113, 2016).
intracerebral hemorrhage (1 paper, 2025). A cerebrovascular disorder characterized by bleeding into one or both cerebral hemispheres including the basal ganglia and the cerebral cortex. "The regulation of CHAC1/BOTCH involves additional molecular players: during intracerebral hemorrhage, inhibition of CHAC1/BOTCH by the androgen receptor (AR) and Jumonji-domain containing protein-3 (JMJD3) led to elevated NOTCH1 levels and exacerbated neuroinflammation." (PMID 41488051, 2025).
intracranial meningioma (1 paper, 2020). A meningioma that arises within the cranial cavity.
ischemic disease (1 paper, 2022). Lack of blood supply to an area of the body, resulting in impairment of tissue oxygenation. "A large amount of evidence indicates that hypoandrogenemia is associated with an increased risk of ischemic disease, and androgen is mediated through the transcriptional control of target genes by androgen receptor (AR)." (PMID 35573679, 2022).
Joubert syndrome 5 (1 paper, 2025). Any Joubert syndrome in which the cause of the disease is a mutation in the CEP290 gene. "Two‐copy number loss of exons 12–15 of CEP290 (MIM# 610142), Joubert syndrome 5 (MIM# 610188, AR), homozygous." (PMID 41477467, 2025). "NM_025114.3(CEP290):c.4792_4795delAAAT, p.K1598Sfs∗8 (#MIM 610142), Joubert syndrome 5 (MIM#610188, AR), homozygous." (PMID 41477467, 2025).
keratitis (1 paper, 2025). A corneal disease that is characterized by inflammation of the cornea. "Adult VKC is similarly linked to heightened inflammation, elevated androgen receptor expression, and greater postoperative keratitis risk from altered flora due to chronic topical steroid application for VKC management." (PMID 40993744, 2025).
lacrimal gland tumors (1 paper, 2015). "In conclusion, androgen-deprivation therapy including the new anti-androgens such as abiraterone and enzalutamide may prove effective treatment options for AR+ lacrimal gland tumors." (PMID 25699235, 2015).
Lipedema (1 paper, 2022). Disorder of adipose tissue characterized by symmetric and bilateral enlargement of the lower extremities due to abnormal deposition of subcutaneous fat often in obese women. "The analysis suggested a significant modification of distinct gene ontology clusters in lipedema, including cytokine-mediated signaling activity, interleukin-1 receptor activity, extracellular matrix organization, and regulation of androgen receptor signaling." (PMID 36605202, 2022).
liver failure (1 paper, 2023). A liver disease characterized by the liver losing or has lost all of its function. "It is probable that SARMs are less likely to result in the development of CVDs or other ailments, such as liver failure, when compared to other anabolic agents, such as T or AASs, because SARMs generally having lower potency and higher selectivity and specificity for the AR." (PMID 37571268, 2023).
lobular breast cancer (1 paper, 2016). "In contrast, infiltrating lobular carcinomas were nearly exclusive to the LAR subtype (4 of 5), suggesting a potential role for AR signaling in lobular breast cancer." (PMID 27310713, 2016).
lymphopenia (1 paper, 2019). Reduction in the number of lymphocytes. "However, we have shown that the activation of genes responsive to AR and GR as well as lymphopenia, likely mediated by epinephrine and corticosterone release are readily apparent after ozone exposure." (PMID 31784596, 2019).
Macular dystrophy (1 paper, 2023). Macular dystrophy is a nonspecific term for retinal degeneration, generally confined to the macula, usually presumed of genetic origin. "In this report of four patients with macular dystrophy and history suggestingStargardt-like disease, two patient’s phenotypes were related to AD genes(RIMS1 and CRX) and those of the other twopatients were related to AR genes (CRB1 andRDH12)." (PMID 36995812, 2023).
male reproductive system disorder (1 paper, 2019). A disease involving the male reproductive system. "Additionally, qualitative and quantitative changes in AR, the primary targets of androgenic steroids, as well as mutations in the gene encoding AR disrupt receptor sensitivity, leading to male reproductive system disorders." (PMID 31018574, 2019).
mammary Paget disease (1 paper, 2015). A malignant neoplasm in which there is infiltration of the skin overlying the breast by neoplastic large cells with abundant pale cytoplasm and large nuclei with prominent nucleoli (Paget cells). "Hormone receptors ER and PR were overexpressed more frequently in mammary Paget's disease, although the single EMPD found in the scrotum had high expression of both ER and AR." (PMID 25692060, 2015).
mesenchymal tumors (1 paper, 2024). "The subtyping revealed predominantly basal-like tumors (IHC-BL, 61%), followed by basal-like immune-suppressed tumors (IHC-BLIS, 31%), mesenchymal tumors (12.5%), luminal androgen receptor tumors (IHC-LAR, 12%), and basal-like immune-activated tumors (IHC-BLIA, 10.9%)." (PMID 38892013, 2024).
mesonephric adenocarcinoma (1 paper, 2013). An adenocarcinoma of the cervix or the vagina arising from mesonephric remnants. "In addition, mesonephric adenocarcinomas are known immunohistochemically to express CD10, calretinin, and androgen receptor, but these immunohistochemical profiles have not been evaluated enough in the sarcomatous component." (PMID 23651629, 2013).
metaplastic breast carcinoma (1 paper, 2021). A group of invasive breast carcinomas characterized by the presence of an adenocarcinomatous component which is admixed with a dominant component that is composed of squamous cells, spindle cells, or mesenchymal cells. "She developed a local chest wall recurrence, biopsy showing a metaplastic breast carcinoma with a component of pleomorphic lobular carcinoma associated with squamous differentiation, ER 20%, PR-, HER2- (IHC 1+ ISH 2.3, ratio 1.1), with androgen receptor staining positive in 30% of tumor cells." (PMID 34168978, 2021).
mucinous tumour (1 paper, 2024). "High androgen levels seem associated with an increased risk of endometrioid and mucinous tumour subtypes yet AR expression is most common in HGSOC and may be protective." (PMID 38994724, 2024).
myoepithelioma (1 paper, 2018). "Regarding AR expression, we detected nuclear AR expression mainly in several benign lesions such as PA and myoepithelioma, but the aberrant AR expression was also identified in several malignant lesions." (PMID 29385707, 2018). "In the context of benign lesions, AR was mainly expressed in PA (33%) and in 28% of myoepithelioma samples, and interestingly in 36% of MEC, in sporadic cases of Ca ex PA, and oncocytic carcinoma." (PMID 29385707, 2018).
nasal polyps (1 paper, 2025). "Moreover, the AR, acting as a nuclear transcription factor receptor, exhibits distribution throughout nasal polyps." (PMID 40894073, 2025). "MRNA and protein levels of PTHLH and CDH3 were notably elevated in nasal polyp tissue compared to the control group, whereas PDCD4 and AR were downregulated (P < 0.05)." (PMID 40894073, 2025).
nephrotic syndrome (1 paper, 2022). A collection of symptoms that include severe edema, proteinuria, and hypoalbuminemia; it is indicative of renal dysfunction. "Genotype-phenotype correlations in pediatric patients with steroid-resistant nephrotic syndrome of AD mutation and AR mutation." (PMID 35755072, 2022).
Noonan syndrome with multiple lentigines (1 paper, 2024). A rare multisystem genetic disorder characterized by lentigines, hypertrophic cardiomyopathy, short stature, pectus deformity, and dysmorphic facial features. "Noonan Syndrome with Multiple Lentigines (NSML) patients, SHP2 knock-in mice, and ACK1 knockout mice presented dramatic increase in pY54-H3, leading to loss of AR transcriptome." (PMID 38965223, 2024).
obstructive uropathy (1 paper, 2019). "During the progression of BPH, AR is required for the proliferation of epithelial and stromal cells, thereby leading to prostate enlargement with obstructive uropathy." (PMID 31052610, 2019).
ocular infection (1 paper, 2025). "Hence, the progesterone receptor or androgen receptor may play a role in the sex-dependent HSV-1 effects that were observed during acute ocular infection and/or explant-induced reactivation in KLF15−/− mice." (PMID 40872334, 2025).
oligoasthenoteratozoospermia (1 paper, 2020). A form of male infertility that is characterized by a combination of low number or oligozoospermia, poor motility or asthenozoospermia, and abnormal shape or teratozoospermia of sperms. "Variant c.2395C>G (p.Gln799Glu) in the AR gene was detected in a man with altered spermogram studies (oligoasthenoteratozoospermia) who started assisted reproduction treatments in 2012." (PMID 32155011, 2020).
ovarian clear cell cancer (1 paper, 2021). An invasive malignant neoplasm that arises from the ovary and is characterized by a predominance of clear and hobnail malignant epithelial cells. "GHSROS knockdown in the ES-2 ovarian clear cell carcinoma cell line, which does not express PPP2R2C, increased the expression of AR (Student’s t-test, P = 0.0029 and P = 0.0022)." (PMID 33585078, 2021).
Ovarian Hyperandrogenism (1 paper, 2014). Increased production of androgens by the ovaries. "They concluded that shorter androgen receptor CAG number is indicative of increased androgen sensitivity, and subsequent ovarian hyperandrogenism." (PMID 24745883, 2014).
PAIS syndromes (1 paper, 2013). "Early detection of the AR mutations known to be usually present in patients with PAIS syndromes or hypofertile men might also significantly improve the hormonal and clinical follow-up of these patients during puberty, especially regarding the size of the penis." (PMID 23637914, 2013).